PIH1D1 (PIH1 domain containing 1)
Description:
Involved in the assembly of C/D box small nucleolar ribonucleoprotein (snoRNP) particles. Recruits the SWI/SNF complex to the core promoter of rRNA genes and enhances pre-rRNA transcription. Mediates interaction of TELO2 with the R2TP complex which is necessary for the stability of MTOR and SMG1. Positively regulates the assembly and activity of the mTORC1 complex.
Synonyms: NOP17; FLJ20643; Pih1; MOT48; DNAAF14
Tractability: PROTAC: ubiquitination databases record sites on it; its protein half-life has been measured.
Gene: Protein-coding gene on chromosome 19 (49,446,291 to 49,453,537, reverse strand). Ensembl gene ENSG00000104872.
Subcellular location: Nucleus
Subcellular location (Human Protein Atlas): Cytosol
Gene Ontology:
Molecular function: ATPase binding; histone binding; histone reader activity; phosphoprotein binding; protein binding; protein kinase binding; RNA polymerase I cis-regulatory region sequence-specific DNA binding
Biological process: box C/D snoRNP assembly; chromatin remodeling; epithelial cell differentiation; positive regulation of glucose mediated signaling pathway; positive regulation of TORC1 signaling; positive regulation of transcription of nucleolar large rRNA by RNA polymerase I; regulation of TORC2 signaling; snoRNA localization; TORC1 complex assembly; protein stabilization; rRNA processing
Cellular component: cytoplasm; nucleolus; nucleus; pre-snoRNP complex; R2TP complex; RPAP3/R2TP/prefoldin-like complex; ribonucleoprotein complex
Genetic constraint (gnomAD): Loss-of-function variants: 26 observed, 35.48 expected, observed/expected ratio (o/e) 0.73, 90% interval 0.54 to 1.02. The upper end of that interval is the gene's LOEUF score, 1.02, which puts it in group 4 of 6, group 1 being the genes least tolerant of losing a copy. Missense variants: 311 observed, 353.22 expected, observed/expected ratio (o/e) 0.88, 90% interval 0.8 to 0.97. Synonymous variants: 137 observed, 142.47 expected, observed/expected ratio (o/e) 0.96, 90% interval 0.84 to 1.11.
Homologues: Orthologues: macaque PIH1D1 (97% identical), chimpanzee PIH1D1 (96% identical), dog PIH1D1 (91% identical), pig PIH1D1 (86% identical), guinea pig PIH1D1 (84% identical), rabbit PIH1D1 (82% identical), rat Pih1d1 (82% identical), mouse Pih1d1 (80% identical), tropical clawed frog pih1d1 (44% identical), zebrafish pih1d1 (37% identical). Paralogues in human: DNAAF2 (21% identical), PIH1D2 (21% identical).
Diseases named in the same sentence as PIH1D1 in open-access papers:
PIH1D1 is named in the same sentence as 5 diseases in open-access papers, as found by Europe PMC text mining. Sharing a sentence is not in itself a finding about the gene and the disease. The quoted sentences say what the papers report.
breast carcinoma (2 papers, 2013 to 2026). "Of these, we focused on amphiregulin, because its probe signal was markedly up-regulated both in RPAP3 and PIH1D1 siRNA-treated cells; moreover, amphiregulin has been reported to have high levels of expression in hormone therapy-resistant breast cancer cells." (PMID 23844004, 2013).
cystic kidney disease (1 paper, 2013). A congenital or acquired kidney disorder characterized by the presence of renal cysts. "These include MORN1 (FAP266) that has been implicated in basal body assembly in Toxoplasma, PIH1D1, which is part of the prefoldin complex and interacting proteins Reptin and Pontin have been implicated in cystic kidney disease in zebrafish and in Chlamydomonas." (PMID 23604077, 2013).
exfoliation syndrome (1 paper, 2021). An autosomal dominant disorder caused by mutations in the LOXL1 gene, encoding lysyl oxidase homolog 1. "Linkage disequilibrium and epistasis analysis for this variant identified the genes LHFPL3, GALNT6, PIH1D1, ANKS1B, and METRNL as potentially involved in the etiopathogenesis of exfoliation syndrome and glaucoma, which were not previously associated with the disease." (PMID 34440405, 2021).
glaucoma (1 paper, 2021). Increased pressure in the eyeball due to obstruction of the outflow of aqueous humor. "In our study, the newly identified linked genes LHFPL3, GALNT6, PIH1D1, ANKS1B, and METRNL may be involved in the etiopathogenesis of XFS and glaucoma." (PMID 34440405, 2021).
cancer (6 papers, 2015 to 2025). A tumor composed of atypical neoplastic, often pleomorphic cells that invade other tissues. "Further analysis revealed that proteins carried by the nanoparticles included various neoantigens derived from mutations recorded in the Catalog of Somatic Mutations in Cancer, such as PlOD2, KEAP1, and PIH1D1." (PMID 39498880, 2025). "WAC expression was also correlated with that of RPAP3 and PIH1D1 (in three out of 10 cancer types), components of R2TP, and we also found some correlation with TTI2." (PMID 40653822, 2025). "Further analysis showed that all of these dysregulated proteins had cancer-related associations, such as PDIA5, DEF6, MZB1, TXNDC5, YARS2, MGST1, and PIH1D1." (PMID 35958927, 2022).